INS (insulin)
Diseases named in the same sentence as INS in open-access papers (continued):
Sharing a sentence is not in itself a finding about the gene and the disease.
Hyperglycemia (continued). "In males with T2DM, 3 × 15 min bouts of activities (175 kcal/each) for daily living post-meal were effective at lowering blood glucose and insulin, but only continuous moderate intensity exercise (50% Wmax; 350 kcal) significantly reduced the time exposed to hyperglycemia (i.e., >10 mM)." (PMID 34069950, 2021). "Hyperglycaemia is also the result of diminished insulin-mediated glucose uptake by skeletal muscle." (PMID 34220705, 2021). "In preterm infants hyperglycaemia can be considered to result from a combination of excess glucose delivery, counter regulatory response to stress and infection, and the impact of prematurity and growth restriction on insulin secretion and sensitivity." (PMID 34368024, 2021). "In small clinical studies, significant GC-exacerbated postprandial hyperglycemia was confirmed through serial blood glucose monitoring, continuous glucose monitoring and the observed higher prandial insulin requirement for normoglycemia attainment in hospitalized patients with DM on GC." (PMID 34529703, 2021). "Therefore, exercise can provide an alternate pathway to increase glucose uptake and lessen blood hyperglycemia in insulin resistant individuals." (PMID 33870263, 2021). "Interestingly, the co-infusion of NMN + OLE resulted in a significant decrease in insulin clearance during basal glycemia and hyperglycemia, compared with SAL infusion." (PMID 34948019, 2021). "Therefore, the goal of this study is to reveal the effects of chronic hyperglycaemia and insulin treatment on TNFα expression in different gut segments and intestinal wall layers." (PMID 34572059, 2021). "Another relevant element affecting NAFLD is hyperglycemia, which stimulates insulin secretion and expands triglyceride synthesis by the liver, resulting in an increase in triglycerides in the blood and a buildup in the liver, leading to progressive liver injury and fibrosis." (PMID 34943908, 2021). "Though these inflammatory responses are detrimental to long-term health in the obese state, increased adiposity, hyperglycaemia and decreased insulin sensitivity favour foetal growth and prepare the mother’s body for the energetic demands of parturition and lactation." (PMID 35128441, 2021). "Moreover, high levels of circulating epinephrine and norepinephrine persist for up to 18–24 months after the acute event and contribute to the so-called chronic shock, characterized, among other things, by long periods of insulin resistance and hyperglycemia." (PMID 34068151, 2021). "The hypoglycaemic effects of medicinal herbs on hyperglycaemia include physiological mechanisms such as enhancing peripheral tissue insulin sensitivity, inhibition of digestive enzymes involved in carbohydrate breakdown and inhibition of glucose absorption in gastrointestinal tract." (PMID 34759766, 2021). "When oral medications are unable to control hyperglycemia to recommended levels, insulin injections may be necessary for T2DM patients." (PMID 34744728, 2021). "We can speculate that Ppy-lineage beta cells with low levels of GLUT2 and UCN3 expression may be generated by the pancreas to survive conditions of metabolic stress under hyperglycaemia, at the expense of glucose-induced INS secretion." (PMID 34498099, 2021). "As there is greater time duration between lunch and dinner, the retrospective correction abates and may even push the prediction downward, resulting in a more conservative insulin delivery and commensurate prolonged hyperglycemia." (PMID 33931977, 2021). "Resulting hyperglycemia would favor the development of an IR state that might require a compensatory effort of insulin production by β cells in a subset of low peripheral disposition of this hormone." (PMID 33801107, 2021). "The positive effect of rAUCins on urea cycle metabolites might be mediated by a reduction of hyperglycemia, which would imply an adequate insulin sensitivity of the liver even in insulin dysregulated horses." (PMID 33575132, 2021).
Hyperglycemia (continued). "Moreover, evidence indicates that TCAs, such as doxepin and amitriptyline, induce hyperglycemia by inhibiting insulin release from the pancreas and inhibit glucose transport, resulting in decreased glucose uptake." (PMID 34564583, 2021). "Thus, it is clearly demonstrated that heparin induces hyperglycaemia by interrupting insulin’s functions." (PMID 34277977, 2021). "Likewise, in diabetic patients with COVID-19, it has been observed that advanced age, the use of insulin for glycemic control, and sustained hyperglycemia contributed to an even worse prognosis." (PMID 34441957, 2021). "Therefore, inadequate insulin or an altered insulin action in target tissues disrupts the metabolic pathways for carbohydrates, proteins and lipids, which can lead to hyperglycemia." (PMID 34361617, 2021). "Conversely, development of new-onset T2DM in HF (cardiogenic DM) is common and has been attributed to an increase in the resistance to insulin, especially in the skeletal muscle, liver, and adipose tissue as well as in diminished insulin secretory response to hyperglycemia by pancreatic β-cells." (PMID 34441977, 2021). "Creatine itself may stimulate insulin secretion in vitro, improve muscle glycogen stores and ameliorate hyperglycemia in animals." (PMID 33572228, 2021). "Moreover, since postprandial insulin also stimulates platelet activation, platelet activation upon hyperglycemia seems to be actually triggered by hyperinsulinemia." (PMID 34992516, 2021). "In addition, systemic inflammation and increased proinflammatory cytokines (e.g., tumor necrosis factor-α, interleukin-1, and interleukin-6) can lead to impaired insulin signaling, thereby exacerbating hyperglycemia." (PMID 34206813, 2021). "It is commonly accepted that GH antagonizes the actions of insulin, where chronic GH excess is associated with hyperinsulinemia, with or without hyperglycemia." (PMID 34685512, 2021). "Fourth, the absence of benefit of CS in our study could be related to the significant increase in the rate of hyperglycemia and in insulin use." (PMID 34347836, 2021). "Insulin is the hormone responsible for regulating hepatic glucose production and glucose storage as glycogen, thus abnormalities in its function lead to hyperglycemia in obese or diabetic patients because of higher production rates and lower capacity to store glucose." (PMID 35002743, 2021). "Both transient and chronic hyperglycemia (>16.7 mM glucose plasmatic levels) trigger in pancreatic β-cells ER stress, leading to failure in the protein maturation process and consequently misfolded both insulin and hIAPP accumulation in the ER lumen." (PMID 34069890, 2021). "Both zebrafish and mouse models of islet miR-21 induction displayed reduced expression of transcription factors specifying β-cell identity and in insulin+ cells, with increases in double positive insulin+ and glucagon+ islet cells, and hyperglycemia or glucose intolerance." (PMID 34246804, 2021). "In addition, hyperglycemia leads to increased blood levels of insulin and insulin-like growth factors (IGF), which promote tumor growth and are targets of novel therapeutics." (PMID 33718132, 2021). "On the other hand, high protein in the diet could delay glucose response and potentially result in hyperglycemia by affecting gluconeogenesis, increasing glucagon secretion and impairing insulin’s ability to suppress endogenous glucose production." (PMID 33918343, 2021). "Notably, it has also been shown that PSC-mediated inhibition of insulin secretion and the resulting hyperglycaemia can in turn provoke further PSC activation." (PMID 34680372, 2021). "The disease originates from multiple factors involving either defects in insulin secretion or errors in insulin action, and sometimes both of these incidences may simultaneously lead to hyperglycemia." (PMID 34445042, 2021).
Hyperglycemia (continued). "Targeting this subunit via specific PI3K inhibitors inhibits the insulin-dependent signaling, which in turn promotes glycogen breakdown in liver and inhibits glucose uptake in skeletal muscle and adipose tissues, resulting in hyperglycemia." (PMID 33801659, 2021). "In addition, no pharmacist asked about other critical information, like the consistency of insulin doses before the onset of the new symptoms, or the presence of fruity-smelling breath that indicates severe hyperglycemia." (PMID 34548092, 2021). "In this case, the pancreatic β cells secrete more insulin to overcome hyperglycemia." (PMID 33718264, 2021). "We propose that the stress response after severe TBI leads to increased levels of catecholamines and decreased insulin secretion, which may lead to hyperglycemia." (PMID 35011926, 2021). "The use of glucagon (GCG) with GLP-1 may intuitively appear contradictory since it antagonizes the effect of insulin and increases glucose levels, evoking hyperglycaemia." (PMID 34072172, 2021). "Overall, these data are suggestive of insulin loss or/and hyperglycemia but not STZ neuronal toxicity as the most putative reasons attributed to predominant biochemical aberrations observed in this work." (PMID 34853620, 2021). "Our results suggest that hyperglycemia is important for development of inflammation and profibrotic processes in the liver, and we show here that insulin administration has beneficial effects on liver pathology and hepatic gene expression in a hyperglycemic, dyslipidemic hamster model of NAFLD." (PMID 33596938, 2021). "Glyburide controls maternal hyperglycaemia by stimulating insulin production." (PMID 33670645, 2021). "Early studies showed that ghrelin stimulates insulin secretion in the presence of hyperglycemia." (PMID 33419065, 2021). "The main strength of the NOD mouse is the presence of spontaneous autoimmunity leading to T1D however, in the mice, this is triggered by the insulin antigen, while in humans this phenomenon is more complex, involving several inducing antigens followed by hyperglycemia." (PMID 33794915, 2021). "Consequently, free fatty acids, especially palmitate, can induce muscle cells and liver cells to become insulin resistant, resulting in hyperglycemia." (PMID 34394985, 2021). "On the other hand, MC from STZ diabetic rats secreted increased amounts of epinephrine and dopamine, but not of norepinephrine (culture medium), and this imbalance was corrected by insulin, demonstrating the important role of hyperglycemia on the development of these alterations." (PMID 34060586, 2021). "Hence, we studied the effect of honey and insulin treatment on hyperglycemia, dyslipidemia, oxidant and anti-oxidant status and nerve conduction in experimental diabetic neuropathy Wistar rats." (PMID 33449943, 2021). "Thus, maternal hyperglycaemia leads to fetal hyperglycaemia and increased insulin secretion which, if persistent, can result in neonatal hypoglycaemia." (PMID 33600450, 2021). "However, the ED that develops alongside hyperglycemia is not only the result of the reduction in NO production by eNOS but also insulin resistance, oxidative stress, and inflammation." (PMID 33995040, 2021). "We normalized the prevailing hyperglycemia in OT2D subjects using an insulin clamp to investigate whether normalization of glycemia normalized the elevated macrophage markers." (PMID 33742062, 2021). "Hyperglycemia may impair β-cells and decrease insulin sensitivity, which were crucial pathophysiological defects in T2DM." (PMID 34136580, 2021). "Despite being much less common compared to T2DM, T1DM is important since once the patient is diagnosed to have had this disease, he/she must take lifelong insulin to control hyperglycemia which is a tremendous burden to the patient, patient’s family, and society." (PMID 33546300, 2021).
Hyperglycemia (continued). "The antioxidant properties of these beverages may exhibit a suppressive effect of hyperglycemia by enhancing insulin sensitivity and subsequently improving a fatty liver." (PMID 34835937, 2021). "Conversely, individuals with T2DM may also experience hyperglycaemia after aerobic or resistance exercise and administer too little insulin for meals before activity." (PMID 33098260, 2021). "This novel preclinical test system, which is characterised by severe hypoxia, excessive ROS levels, hyperglycaemia and insulin withdrawal, can serve as a surrogate assay for probing the efficiency of candidate WH promoters under well-standardized and clinically relevant ex vivo conditions." (PMID 32572565, 2021). "The lack of pronounced effects on food intake, water intake and serum insulin and hyperglycemia in the present study could be attributed to a couple of factors." (PMID 34947993, 2021). "The gerbils in the Control group had post-stroke hyperglycemia due to decreased insulin sensitivity and β-cell function and mass; the CKJ291, CSB, and CKJ1 treatments protected against glucose disturbance after artery occlusion and were similar to the Normal-control." (PMID 34828975, 2021). "On the other hand, severe SARS-CoV-2 infection and its associated hyperinflammation contribute to hyperglycemia through an indirect negative effect on insulin target tissues and a potential direct negative effect on pancreatic β-cells." (PMID 34220706, 2021). "APD-elevated glucagon may therefore drive the hyperglycemic states that these drugs produce since glucagon receptor KO mice are protected against APD-induced hyperglycemia independently of changes in insulin levels." (PMID 33589583, 2021). "However, AAV-BMPER injection led to the normalization of hyperinsulinemia and hyperglycemia, improved glucose clearance and insulin sensitivity, and decreased TG and DAG contents in db/db mice." (PMID 33772019, 2021). "Long-term doxepin use can promote hyperglycemia induced by decreases in insulin signaling." (PMID 33809508, 2021). "Insulin is a commonly used drug to treat hyperglycemia, but excessive use of insulin could lead to frequent hypoglycemia and greatly increase the mortality of patients with sepsis." (PMID 34335269, 2021). "Pancreatic enlargement has been detected in SARS-CoV-2 infected patients possibly affecting insulin production and causing hyperglycemia in non-diabetic patients." (PMID 34202952, 2021). "Furthermore, while all three mouse models of MS displayed improvement in hyperglycemia, a significant reduction in plasma insulin after mAb treatment was observed only in DIO mice." (PMID 33904407, 2021). "Consistent with the worsening of hyperglycemia, pancreatic islet density, β-cell number, proliferation, and survival, as well as circulating insulin levels were reduced, whereas α-cell number and pancreatic inflammation were increased in the absence of PRL signaling." (PMID 33746901, 2021). "In terms of the mechanisms underlying hyperglycemia and hyperinsulinemia induced by PEPCK overexpression, it appeared that lipid accumulation in the liver functioned to inhibit glucose metabolism and decrease hepatic insulin extraction." (PMID 34943809, 2021). "Thus, GDM is defined as hyperglycemia first recognized in pregnancy and can be seen as consequence of an insulin supply inadequate to meet the demands for normal blood glucose regulation." (PMID 34884524, 2021). "Targeting both GLP-1 and insulin secretion with a SSTR5 antagonist could perhaps be an advantage in the treatment of hyperglycemia in humans." (PMID 33434183, 2021). "The most widely debated theory is that SARS-CoV-2 infects the pancreas via ACE2 interaction on pancreatic β cells, which then impairs endogenous insulin synthesis by altering insulin receptor signaling, resulting in acute hyperglycemia and devastating hyperinflammation." (PMID 34681689, 2021).
Hyperglycemia (continued). "Several factors may explain the mechanisms underlying the pathological and functional changes in liver injury-induced hyperglycemia, including insulin resistance, inflammation, and oxidative stress." (PMID 34141709, 2021). "Intriguingly, a significant genotype vs. lipid-treatment interaction with reduced glycogenolysis and less severe hyperglycemia was observed in Ala/Ala94 carriers, suggesting less impaired insulin signaling due to reduced hepatocellular uptake of lipotoxic FFA species." (PMID 34359991, 2021). "It has been shown that chronic hyperglycemia leads to the decrease of insulin biosynthesis and secretion due to β-cell glucose toxicity and that the reduction of insulin mRNA expression is accompanied by decreased nuclear expression of insulin transcription factors such as MafA and PDX-1." (PMID 34360682, 2021). "More importantly, the delivery of BMPER recombinant protein or its adeno-associated viral (AAV) particles dramatically alleviates insulin resistance and hyperglycemia in diabetic mice." (PMID 33772019, 2021). "However, if insulin resistance of the cells increases, insulin is unable to efficiently lower the blood glucose levels, leading to hyperglycemia." (PMID 34501978, 2021). "However, in last year, she presented some episodes suggestive of minor ketosis hyperglycemia decompensation, making it necessary guidelines for its correction with insulin and prescription of oral medication." (PMID 33905625, 2021). "In previous studies, we reported evidence showing that chronic cola consumption in rats impairs pancreatic storage of insulin and glucagon and produces some alterations related to metabolic syndrome (hyperglycemia and hypertriglyceridemia) with an increase in oxidative stress." (PMID 34115756, 2021). "For example, significant associations were observed between the tagSNPs of the AVP gene (CC genotype of rs6084264, the TT genotype of rs2282018, the C-allele of rs2770381, and the CC genotype of rs1410713) and the incidence of hyperglycemia and decreased insulin sensitivity." (PMID 33905792, 2021). "TCA's downregulation of these inflammatory genes may have resulted in reversing the dysregulation of insulin signalling, concomitantly reducing hyperglycaemia and its resultant oxidative and inflammatory effects." (PMID 34956587, 2021). "Notably, glucocorticoid, which is an essential medication to control CRS in COVID-19, impairs insulin sensitivity and result in hyperglycemia too." (PMID 34690930, 2021). "Induction of hyperglycemia results in elevated levels of insulin." (PMID 34611148, 2021). "Insulin doses may need to be titrated more often and additional correction boluses of fast‐acting insulin may be required to avoid severe hyperglycaemia and ketoacidosis." (PMID 34268455, 2021). "Furthermore, anti-sense oligonucleotides directed against the GR have shown liver-specific effects, decreasing fasting hyperglycemia, reducing fasting insulin levels and decreasing GC-stimulated hepatic glucose output." (PMID 33435513, 2021). "Basal hyperglycemia occurs when there is a lower insulin-to-glucagon ratio owing to the increased production of glucose by the liver, whereas postprandial hyperglycemia arises due to a decrease in plasma insulin concentration or action that reduces glucose utilization in peripheral tissues." (PMID 34203830, 2021). "High energy and nutritional requirements and variable insulin sensitivity in preterm infants makes preventing hyperglycaemia, without the risk of hypoglycaemia, challenging." (PMID 33577770, 2021). "However, some studies confirmed that hyperglycemia, the insulin/insulin-like growth factor (IGF) axis and inflammatory cytokines play important roles in promoting EC proliferation and invasion." (PMID 34975754, 2021). "Finally, we believe that there is a population of patients who require insulin therapy at diagnosis—specifically, those with symptomatic hyperglycemia and/or HbA1c > 9.0%." (PMID 33910583, 2021).